SMARCB1 (SWI/SNF related BAF chromatin remodeling complex subunit B1)
Diseases named in the same sentence as SMARCB1 in open-access papers (continued):
Sharing a sentence is not in itself a finding about the gene and the disease.
tumor (continued). "The phosphoproteomic results suggested that in Smarcb1 deficient tumor cells phosphorylation of ErbB signaling cascade and EGFR itself persists even upon serum withdrawal." (PMID 26370283, 2015). "We further identify multiple biological networks and kinases whose regulation is altered in Smarcb1 deficient tumor cells in a Smarcb1 dependent manner." (PMID 26370283, 2015). "Accordingly we found that Smarcb1 deficient tumor cells are specifically vulnerable to AKT or PI3-kinase inhibition." (PMID 26370283, 2015). "Tumor-specific mutations in the following SMARCs are especially common: SMARCB1/SNF5, SMARCA2/BRM, and SMARCA4/BRG1." (PMID 24622842, 2014). "ATRT tumor from proband case displayed a biallelic inactivation of SMARCB1/INI1 gene by heterozygous loss of one allele and Arg40X mutation in the exon 2 of the second allele." (PMID 23510391, 2013). "We then associated the SMARCB1/INI1 expression patterns with patients’ clinico-pathological features, immunohistochemical and molecular markers of tumor differentiation." (PMID 24286138, 2013). "SMARCB1, located in chromosome band 22q11.2, is a tumor suppressor gene that encodes the INI1 protein." (PMID 22567403, 2012). "Whether this subset represents ES or MRT with MET features, or a histologically distinct MET-like tumor with SMARCB1 loss is unclear currently and requires further investigation." (PMID 39636306, 2025). "The fact that germline SMARCB1 PVs not only predispose to SWN but also to highly malignant pediatric tumours in the context of RTPS1, indicates that cells of different origin must be vulnerable to the complex cellular, molecular and developmental disturbances resulting from SMARCB1 loss." (PMID 40794298, 2025). "Indeed, SMARCB1-deficient MRT cells are unable to remove repressive PRC2-mediated histone modifications such as H3K27Me3 from tumour suppressor genes, for example CDKN2A (MIM #600160)." (PMID 40794298, 2025). "An emerging metabolic target in SMARCB1-deficient tumours is the cholesterol biosynthetic pathway." (PMID 40422882, 2025). "SMARCB1 loss may increase tumor mutational burden and immunogenicity, suggesting potential responsiveness to immunotherapy." (PMID 40225550, 2025). "One such promising approach involves targeting PRC2 with EZH2 inhibitors, which could counteract the tumor-promoting effects of SMARCB1 loss." (PMID 40076599, 2025). "In addition, TTI-101, an inhibitor targeting STAT3, significantly inhibited tumor growth and metastasis in a SMARCB1-deficient tumor model." (PMID 39995416, 2025). "Moreover, in MRT cells, EGFR-TKIs such as Lapatinib or Gefitinib reduce cell proliferation and hinder tumor activity in SMARCB1-deficient cells and tumors." (PMID 39971779, 2025). "The tumor was eventually diagnosed as a PXA with SMARCB1 deficiency." (PMID 40231261, 2025). "Thus, SMARCB1-deficient malignant melanocytic intraocular tumours would appear to be part of the spectrum of RTPS1-associated tumours." (PMID 40794298, 2025). "The tumor cells show a loss of SMARCB1 (INIl) expression or SAMRCA4 expression." (PMID 40002892, 2025). "In addition to MRTs, many other tumour types exhibit somatic SMARCB1 gene inactivation or loss of expression; this group of malignancies has been collectively defined as SMARCB1-deficient tumours [reviewed by 18–20]." (PMID 40794298, 2025). "Integrating metabolomic profiling into future studies may uncover additional biomarkers and enable the development of metabolism-targeted therapies in SMARCB1-deficient tumours." (PMID 40422882, 2025).
tumor (continued). "However, tamoxifen injection and thus biallelic Smarcb1 loss between E6 and E10 resulted in viable mice which developed mainly intracranial tumours with high penetrance and rapid onset." (PMID 40794298, 2025). "SMARCB1 mutations can also be detected using NGS assays on tumor tissue." (PMID 40564017, 2025). "This would logically lead to the differentiation of SMARCB1-deficient tumor cells." (PMID 40862786, 2025). "Additionally, the timing of the tumour-specific inactivation of the SMARCB1 wild-type allele and the loss of additional tumour suppressor genes are responsible for the differences in tumorigenesis in SWN compared with RTPS1." (PMID 40794298, 2025). "Additionally, SNF5/BAF47 (it is encoded by the SMARCB1) has traditionally been regarded as a tumour suppressor protein capable of exerting tumour suppression by inhibiting MYC activity." (PMID 39779467, 2025). "In another tumour model using human SMARCB1-deficient pluripotent stem cell-derived neural progenitor-like cells (NPLCs), brain tumours could be induced after the NPLCs were transplanted into the mouse brain." (PMID 40794298, 2025). "Thus, the tumour phenotype associated with germline SMARCB1 PVs is determined by the nature and location of the SMARCB1 mutation and the timing of SMARCB1 inactivation in specific progenitor cells." (PMID 40794298, 2025). "SMARCB1-deficient carcinoma is a newly proposed gene-related malignant solid tumor with a clear genotype, which is a relatively well-diagnosed and independently classified tumor among the undifferentiated cancers of the head and neck." (PMID 40115023, 2025). "Consequently, mutations in SMARCB1 drive aberrant gene expression programs thereby promoting tumor cell proliferation and metastasis." (PMID 37999735, 2024). "SMARCB1/INI1 expression was deficient in the nuclei of tumor cells." (PMID 39398818, 2024). "Notably, the tumor cells showed complete loss of INI-1 (SMARCB1 protein), which is normally expressed in the nucleus." (PMID 38217014, 2024). "This study reports a case of SMARCB1-deficient tumor in the right parapharyngeal space." (PMID 39398818, 2024). "In contrast, one patient died 11 months after initial resection with multifocal intracranial disease; however, this tumor additionally harbored a subclonal SMARCB1 mutation and clusters of embryonal cells making it histologically and molecularly distinctive from the other cases." (PMID 39228008, 2024). "Additionally, we examined the molecular mechanisms of metastasis and examined therapeutic strategies to overcome tumor growth and metastasis in SMARCB1-deficient BLCA driven by STAT3 pathway upregulation." (PMID 38355560, 2024). "There was loss of SMARCB1/INI1 expression in the tumor cells." (PMID 39677208, 2024). "Importantly, almost all renal rhabdoid tumors show biallelic loss of SMARCB1 and thus this is one of the universal features of this tumor type." (PMID 37999735, 2024). "A homozygous frameshift SMARCB1 mutation in a SCCOHT tumour has also been reported." (PMID 39272926, 2024). "Among the MRT xenografts studied, all but RBD1 were deficient in SMARCB1 at both protein and RNA levels, with five out of six models showing objective tumor responses (one maintained complete response (MCR), two complete responses (CRs), and two partial responses (PRs))." (PMID 38893160, 2024). "Furthermore, a pSTAT3 selective inhibitor, TTI-101, reduces tumor growth in SMARCB1 KO orthotopic cell line-derived xenografts and a SMARCB1-deficient patient derived xenograft model." (PMID 38355560, 2024). "Recurrent tumors showed a pathogenic SMARCB1 copy number loss on repeat sequencing more consistent with ATRT (not present on the initial diagnostic tumor specimen) while retaining the molecular features of the original tumor." (PMID 38639853, 2024). "In this study, we reported a rare case of a SMARCB1-deficient tumor in the parapharyngeal space." (PMID 39398818, 2024).
tumor (continued). "In addition to the SMARCA4 mutation and retained SMARCA4 expression, the primary tumor in this study also displayed partial loss of SMARCB1 and SMARCA2 expression." (PMID 38201285, 2023). "However, we hope that this short report will prompt others to undertake methylation profiling on SMARCB1‐deficient tumours, as the classification of disease has important implications for treatment." (PMID 37316954, 2023). "In addition, we occasionally found tumor-like Smarcb1-deficient areas at the junction of the midbrain and the posterior fossa, which never reached the bulky volume observed in the basal ganglia region." (PMID 37863903, 2023). "This unique environment may explain why RMC is the only SMARCB1-deficient tumour arising from epithelial cells, differentiating RMC from rhabdoid tumours arising from neural crest cells." (PMID 37236926, 2023). "Interventional trials could enroll multiple rare tumor types based on mutation status, such as the recently opened trial for SMARCB1/SMARCA4-deficient tumors (NCT05286801)." (PMID 37966258, 2023). "The most common site of this type of tumor was the stomach (13 cases), followed by the colon (11 cases), small intestine (10 cases), and esophagus (5 cases), although not all of the previously reported cases involved the loss of SMARCB1." (PMID 36732357, 2023). "A prior study in MRT models demonstrated that pevonedistat could induce a cytotoxic response through upregulation of the unfolded protein response in SMARCB1‐deficient tumours." (PMID 37226898, 2023). "In addition, emerging evidence indicates that immunotherapy, including immune checkpoint inhibitors, represents a promising therapeutic strategy for SMARCB1‐deficient tumours." (PMID 37316954, 2023). "This unique set of circumstances may explain why RMC is the only SMARCB1-deficient tumour arising from epithelial cells, compared to RTs arising from a developmental block of neural crest differentiation." (PMID 37236926, 2023). "This second group challenges the consequences of a Smarcb1 loss described in literature (e.g., in tumour cells), loss of BAF binding and repression of genes via PRC2 activity, and in this way suggest the existence of additional mechanisms by which BAF complexes control gene repression." (PMID 35456033, 2022). "The interim results from the ongoing KEYNOTE-051 phase I-II trial have shown that one of two MRT patients included in the study demonstrated a response to pembrolizumab, while the only patient with epithelioid sarcoma, another SMARCB1-deficient tumour, also responded to treatment." (PMID 35327375, 2022). "The pathogenesis of these tumors is incompletely understood, but the hypoxic milieu in the kidney may confer a particular susceptibility for genomic instability, loss of the SMARCB1 (also known as INI1) protein and thus tumor formation." (PMID 36291828, 2022). "The 5th Edition of the WHO Classification of CNS Tumours introduced CRINET as a provisional diagnosis; it is a non‐rhabdoid neuroectodermal tumor with a prominent cribriform arrangement of tumor cells that have characteristic loss of INI1 due to homozygous loss‐of‐function of SMARCB1." (PMID 35266242, 2022). "In this review, we outline key mechanisms by which loss of SMARCB1 may lead to tumor formation and cover how these mechanisms have been used for the design of targeted therapy." (PMID 35892904, 2022). "This tumor subtype most often presents with compound point mutations in both SMARCB1 alleles." (PMID 35892904, 2022). "Importantly, Smarcb1 alterations are linked to neurodevelopmental disorders and tumours of the developing brain such as atypical teratoid rhabdoid tumours (AT/RT)." (PMID 35456033, 2022).
tumor (continued). "Smarcb1 disruption is early embryonic lethal and mice with heterozygous disruption of Smarcb1 develop tumors which exhibit loss of heterozygosity, indicating that SMARCB1 is a bona fide tumor suppressor." (PMID 35323214, 2022). "Brachyury could serve as a reliable marker distinguishing pediatric PDC from other three SMARCB1/INI1-deficient tumor types." (PMID 35804041, 2022). "Here, all cases studied had SCT and all tumor samples had loss of SMARCB1 based on IHC." (PMID 35806102, 2022). "Emerging evidence suggests that SMARCB1-deficient cancers may have anti-tumor immunogenicity and may be susceptible to immunotherapy." (PMID 35892904, 2022). "This tumor, like other SMARCB1-deficient tumors, exhibits rhabdoid or plasmacytoid cytomorphology." (PMID 36415387, 2022). "Notably, the complete expression loss of SMARCB1/INI1, one of the best know tumor suppressors, has also been demonstrated in ES." (PMID 34681807, 2021). "In the meantime, SMARCB1 underexpression was more likely linked to a hypodiploid tumor genome." (PMID 32380731, 2020). "To validate the dependency of SMARCB1 deficient tumors to the ubiquitin-proteasome system, we assessed the consequences of inhibiting proteasome function on survival of the primary tumor cell line, CLF_PEDS0005_T1, by deleting components of the proteasome with CRISPR-Cas9." (PMID 30860482, 2019). "In SMARCB1/SNF5-deficient tumor cells, EZH2 inhibitor treatment can increase p16INK4a expression by lowering the level of tri-methylated H3K27 in the p16INK4a gene region, which demonstrates that EZH2 epigenetically silences the expression of p16INK4a by catalyzing H3K27 tri-methylation." (PMID 31590683, 2019). "In rhabdoid tumor cells, the loss of SMARCB1 compromises SWI/SNF opposition of Polycomb repression." (PMID 31123059, 2019). "Importantly, EZH2 is essential for tumor formation after conditional loss of SMARCB1 in mice, and treatment with small molecule EZH2 inhibitors led to regression of RT in a xenograft model." (PMID 31123059, 2019). "While biallelic loss of Smarcb1 leads to early lethality during mouse development, haplo-insuffient mice are prone to develop tumors that resemble human RTs, showing loss of heterozygosity that is typical for a tumor suppressor." (PMID 31123059, 2019). "The discovery that the phosphorylation of multiple transcription factors is upregulated in SMARCB1-deficient parental A204 rhabdoid tumour cells is consistent with the role of SMARCB1 in organising nucleosome structures surrounding transcriptional start sites in a genome-wide manner." (PMID 28842319, 2018). "In the present study, we report mutations in known tumor suppressor genes such as SMARCB1 and ATM." (PMID 30093964, 2018). "Furthermore sinonasal basaloid carcinomas and neoplasms arising from the gastrointestinal tract, pancreas and uterus with SMARCB1 deficiency have been reported." (PMID 29625594, 2018). "Pediatric AT/RT is the most major tumor of SMARCB1 deficiency." (PMID 29625594, 2018). "The sequence result showed copy number loss of SMARCB1 gene in this tumor." (PMID 29625594, 2018). "In addition to the TFE3 rearrangement, the tumor cells showed the complete loss of SMARCB1 expression." (PMID 27733182, 2016). "Abbas Agaimy proposed that SMARCB1 deficient neoplasms were possibly derived from different progenitor cell subsets with different differentiation commitments in the different organs, and thus probably were genetic subtypes of tumors with certain differentiation." (PMID 27733182, 2016). "Interestingly, Smarcb1-deficient intracranial tumours from our model showed even higher AGDEX correlation scores when compared with hIC and hEC (0.67 and 0.68, respectively), confirming their relevance to human RTs." (PMID 26818002, 2016). "Although the lower recombination rate in brain after E10 may influence penetrance, Smarcb1-deficient cells can be observed at E12 but cannot give rise to tumours." (PMID 26818002, 2016).
tumor (continued). "The SILAC (Stable Isotopic Labeling of Amino Acids in Cell Culture) protocol was used to quantify in an unbiased manner any changes in the phosphoproteomic profile of Smarcb1 deficient murine rhabdoid tumor cell lines following Smarcb1 stable re-expression and under different serum conditions." (PMID 26370283, 2015). "Interestingly, several of these germline variants were found to be expressed in the tumour, including the nonsense mutation in SMARCB1." (PMID 26998479, 2015). "A previous study done on SMARCB1-deficient tumor cells revealed persistent AKT activation." (PMID 26347853, 2015). "We also searched for additional germline mutated genes other than SMARCB1, which could contribute to tumour predisposition." (PMID 26998479, 2015). "Similarly, investigations into the role of inactivating mutations in chromatin modifiers (i.e. KDM6A, CREBBP/EP300, SMARCB1) implicate many of these genes as tumor suppressors." (PMID 24622842, 2014). "However, applying DMS to tumor suppressors like SMARCB1, which exhibit low somatic mutational frequencies, remains an underexplored avenue that could provide insights into SWI/SNF biology and inform cancer diagnostics." (PMID 40196006, 2025). "Furthermore, EZH2 appears to be dysregulated and aberrantly expressed in SMARCB1-deficient tumours, suggesting it may act as a druggable dependency." (PMID 40983796, 2025). "However, the effectiveness of tazemetostat in SMARCB1-deficient sinonasal tumors, a type of SMARCB1-deficient tumor in the head and neck region, remains unclear." (PMID 39398818, 2024). "As the diagnosis of this tumor coincided with incipient puberty, it is tempting to speculate that the associated changes in systemic growth stimuli facilitated the manifestation of these indolent SMARCB1-null cells." (PMID 38501975, 2024). "In addition, pre-clinical and clinical evidence suggests that a subset of SMARCB1-deficient tumours may be immunogenic." (PMID 39796641, 2024). "Additionally, sharp, punched-out vacuoles within tumor sheets, yolk sac-like morphology, and pagetoid spread along the surface epithelium may be seen in SMARCB1-deficient carcinomas that may aid in diagnosis when present." (PMID 36941503, 2023). "However, it is the residual BAF complexes deficient in SMARCB1 which drive tumor formation." (PMID 37093326, 2023). "Taken together, Snr1 knockdown in engrailed expressing cells causes aberrant hedgehog and Notch signaling and is associated with formation of tumor-like structures in the fly model, suggesting that SMARCB1-deficiency may have a similar role on SHH and Notch activation in human ATRT–SHH." (PMID 35501487, 2022). "We notably discuss the heterogeneity that exists among the spectrum of malignancies driven by SMARCB1-loss, and highlight challenges that are at stake for developing a personalized immunotherapy for these tumors, notably using molecular profiling of the tumor and of its microenvironment." (PMID 35327458, 2022). "Moreover, it will be important to examine the generalisability of our findings to other tumours driven by the biallelic loss of SMARCB1 and other members of the BAF chromatin-remodelling complex, in particular AT/RT which are considered to be the intracranial counterpart of MRT." (PMID 33658498, 2021).